IL17A (interleukin 17A)
Diseases named in the same sentence as IL17A in open-access papers (continued):
Sharing a sentence is not in itself a finding about the gene and the disease.
tumor (continued). "Inflammatory Th17 cells and their associated cytokines (i.e., IL-17A, IL-17F, IL-21, IL-22, etc.)mediate tumor growth in two distinct ways – by driving angiogenesis and by suppressing antitumor immunity." (PMID 24987392, 2014). "Intranasal treatment of mice with a neutralizing anti-IL-17A antibody in experimental lung adenocarcinoma caused a significant reduction of tumor growth as compared to control treated mice." (PMID 24872958, 2014). "Consistent with this, IL-17A-deficient C57/Bl6 mice are characterized by a reduced Stat3 activation, as well as increased numbers of tumor infiltrating CD4+ and CD8+ T cells, which produce higher amounts of IFN-γ as compared to wild-type littermates." (PMID 22855687, 2012). "As a consequence, those IL-17A-deficient mice showed a reduced tumor growth rate in case of B16 melanoma as well as in case of MB49 bladder carcinoma." (PMID 22855687, 2012). "The frequency of IL-17A-positive cells in tumor tissue was associated with HCC metastasis and prognosis." (PMID 21760911, 2011). "The founding member of this family, IL-17 (or IL-17A), has also been implicated in promoting tumour angiogenesis through the induction of other proangiogenic factors." (PMID 20467469, 2010). "Overall, the interleukin profiles indicate that IL-8 and IL-33 are more closely associated with localized or intermediate stages of tumor invasion, while IL-17A demonstrates a steep decline in advanced disease, potentially reflecting immune suppression during metastatic progression." (PMID 40725273, 2025). "IL-17A has also been implicated in promoting resistance to immunotherapy and chemotherapy, such as cisplatin, by enhancing tumor cell survival and suppressing anti-tumor immunity." (PMID 40725273, 2025). "While IL-17A is largely associated with tumor progression and metastasis—especially in the aggressive CMS4 subtype—IL-17F may exhibit anti-tumor activity in early-stage CRC by supporting cytotoxic T cell function." (PMID 41244711, 2025). "Moreover, IL-17A polymorphisms have been associated with tumor location and progression, highlighting their potential as both biomarkers and therapeutic targets." (PMID 40725273, 2025). "We found that in mice, downregulation of IL-17A expression in A549 cells prevented bone destruction caused by tumor metastasis in vivo, with a significant reduction in the number of osteoclasts on the bone surface in mice injected with IL-17A-deficient A549 cells." (PMID 38394046, 2024). "This study suggests that suppressing IL-17A could potentially decrease tumor progression associated with STAT1 deficiency." (PMID 39411241, 2024). "In addition, dual oxidase 2 (DUOX2), a gene whose expression is differentially modulated by IL‐17A, was primarily detected in tumor cell clusters derived from mice with IL‐17RA deficiency." (PMID 38585232, 2024). "However, similar to Foxp3+CD4+ T cells data, the presence of IL17A+CD4+ T cells in the tumour microenvironment is associated with potential anti-tumour, as well as pro-tumourigenic effects due to their plasticity." (PMID 39409156, 2024). "Interestingly, evaluating the association between CD8+ immune phenotypes and tumour stroma, infiltrating PD-L1+ lymphocytes, repeated the trends seen in the IL17A+CD4+-immune phenotype, but the statistical significance was not reached." (PMID 39409156, 2024). "Our results showed elevated plasma levels of FGF, IL-6, IL-8, M-CSF, VEGF, TNF-alpha, and IL-17a, molecules previously associated with larger tumor size, metastasis, and poor prognosis, as well as persistent HPV infection in older women with evidence of an immune deficit." (PMID 38114557, 2023). "The results also showed that IL‐17A might be associated with tumor load and tumor invasiveness of HBV‐HCC." (PMID 37153113, 2023). "In addition, serum IL-17A was significantly elevated in MNU and H. pylori- treated mice compared with control, suggesting an association of serum IL-17A with H. pylori-induced tumor development in our model." (PMID 36125689, 2023).
tumor (continued). "Accordingly, IL-17A/F secreted by pathogenic Th17 cells has been shown to contribute to the growth and metastasis of numerous cancers via increased secretion of IL-6 by tumor cells and tumor-stromal cells, resulting in Stat-3 activation." (PMID 37296927, 2023). "Also, IL-17A has recently been suggested to have a pro-survival effect on tumor cells in various cancers, and several studies of mice transplanted with cancer cells deficient in either IL-17A or its receptor report inhibition of tumor growth." (PMID 38062130, 2023). "Finally, the influence of CTSK and IL-17A on tumor-associated macrophages M2 in PC tissues was verified by database analysis and appropriate experiments." (PMID 36138018, 2022). "Furthermore, a decrease in the levels of IL-17A caused by treatment with endothelin-1 receptor dual antagonist led to the slowdown of the growth of 4T1 tumor." (PMID 35954312, 2022). "The mechanisms underlying the anti-tumor effects of IL-17A are poorly understood." (PMID 36098359, 2022). "The prevalence of a specific pool of Th1.17 cells at the tumor site after the use of MDR1-associated chemotherapy may indeed contribute to the manifestation of the antitumor properties of IL-17A." (PMID 36297616, 2022). "In the intestinal tract, tumor-associated bone marrow cells secrete IL-23, which affects the polarization of Th17 cells, followed by the production of IL-17A, IL-21, TNF-α, and IL-6, which induce a tumor-promoting inflammatory response and promote CC development." (PMID 36147322, 2022). "In addition to IL-17A, numerous clinical trials have implicated the function of the IL-17B/IL-17 receptor B (IL-17RB) pathway in tumor formation and chemoresistance." (PMID 36313570, 2022). "IL-17A has been shown to promote the growth of MM cells, but also to inhibit immune functions in the tumour environment, which underlines the important role of this cytokine in tumour growth and maintenance." (PMID 33808304, 2021). "LYC-53772 and LYC-54143, as potent RORγ synthetic agonists, can boost the differentiation of Th17 cells, block immunosuppression driven by Tregs and significantly elevate the level of secreted cytokines, including IL-17A, IL-17F, and GM-CSF, and IL-22, such that an anti-tumor activity is implicated." (PMID 33752691, 2021). "In conclusion, we demonstrate that IL17A neutralization represents a novel strategy to shape tumor-associated macrophages and might potentiate the gemcitabine effect on these cells." (PMID 33802061, 2021). "In addition to the direct effects of TGF-β1 signaling on HNSCC cells, TGF-β1 together with interleukin-17 (IL-17A) primes tumor-associated neutrophils to adopt a tumor-promoting phenotype and induce EMT-related functional changes in OSCC." (PMID 34771518, 2021). "Additionally, increased levels of tumour-associated neutrophils (TANs) have been linked to GC, and TANs which produce IL-17A have been associated with EMT of GC cells and predict poor prognosis." (PMID 34944729, 2021). "The lower Th17 densities in AAs vs. CAs could lead to mucosal barrier compromise and increased microbial translocation, while the trend toward higher IL17a responses may reflect an inflammatory reaction to tumor associated microbes." (PMID 33987094, 2021). "In addition, tumor-associated neutrophils contribute to GC cell migration and invasion through IL-17a-induced EMT." (PMID 34281542, 2021). "In addition, lung metastasis was shown to be suppressed by IL-17A deficiency or IL-17A blockade in tumor models." (PMID 32203101, 2020). "IL-17a has pro-tumor actions, which is associated with angiogenesis." (PMID 32554855, 2020). "In one study, deletion of the genes encoding either IL-17A or its receptor (IL-17AR) was found to confer protection against tumor promotion and progression, while combining administration of an anti-IL-17A MAb together with chemotherapy was found to enhance therapeutic efficacy." (PMID 31616428, 2019).
tumor (continued). "We observed that IL-17A signal in the tumor and the stromal areas significantly associated with nuclear NF-κB staining (r = 0.46, p=0.04; r = 0.53, p=0.01; Pearson); therefore, we concluded that IL-17A/NF-κB axis would be involved in LSCC′ epithelial to mesenchymal transition." (PMID 31885577, 2019). "However, despite the fact that also other cells express Ifnγ and Il17a, the examination of T-cell effector molecules revealed decreased Ifnγ and Il17a expression in obese IL-6Rα-deficient tumours that have been restored upon Treg depletion." (PMID 29695802, 2018). "Besides, blocking mast cells degranulation and associated-IL-17A can inhibit tumor growth and GC progression in vivo." (PMID 30305610, 2018). "Thus, ONX 0914 treatment as well as LMP7 deficiency probably influence IL-17A cytokine levels in ApcMin/+ mice, thus suppressing tumor growth." (PMID 28881611, 2017). "Existing literature data suggest that Th17 and Tc17 cells can mediate potent and durable tumor growth inhibition when transferred to tumor-bearing animals and their hallmark cytokines such as IL-17A and GM-CSF are associated with improved antitumor effects in some cancers." (PMID 28123897, 2016). "However, it did affect the tumor microenvironment by increasing secretion of IL-17A, which is a hallmark cytokine of Th17 cells." (PMID 25349535, 2014). "Similarly, IL-17A deficiency or IL-17A blockade led to suppression of lung metastasis in tumor models." (PMID 24872958, 2014). "This increased capacity of LPL to produce IL-17A in treatment-resistant RCDII may be related to the continued inflammation and risk of EATL development, as IL-17A is involved in chronic inflammation as well as in tumour formation." (PMID 23690672, 2013). "The role of local IL-17A might indicate parallel development of inflammation, causing angiogenesis and immunosuppression in tumor microenvironment." (PMID 23372655, 2013). "Interestingly, high frequency of IL-17A-positive cells in tumor tissue was significantly associated with patient's metastasis (P = 0.002), overall survival rate (P = 0.01) and disease-free survival rate (P = 0.03)." (PMID 21760911, 2011). "Additionally, IL-17A upregulated a range of other tumor-associated genes and signaling pathways." (PMID 40280932, 2025). "Therefore, low IL-17A expression at 21 dpi provided by the infusion of activated PBMCs may be associated with the prevention of tumor formation by MDV." (PMID 36851499, 2023). "However, in a model in which the deletion of phosphatase and tensin homolog deleted on chromosome ten (Pten) and SMAD family member 4 (Smad4) from airway epithelial cells results in the development of spontaneous tumors, tumor incidence was increased in mice deficient for IL-17A." (PMID 35883573, 2022). "In addition, IL-17A levels have been associated with higher tumour vessel density and more advanced cancer stage, thus raising the hypothesis that IL-17A could be involved in malignancy progression." (PMID 34640589, 2021). "Indeed, IL-17A T cells have been linked to tumor invasion and metastasis in lung adenocarcinoma." (PMID 33375062, 2020). "IL-17A production can dismantle the anti-tumor functionality of IFNγ-producing γδ T cells, and Tγδ17 cells have been associated with tumor progression and poor outcomes in multiple tumor types; however, the mechanism by which this occurs in humans is not fully understood." (PMID 33255339, 2020). "Additionally, AOM/DSS-treated IL-17A-deficient mice with CAC show reduced tumor development." (PMID 32357539, 2020). "Interestingly the analysis also showed that IL-17A expression in the tumor and the stromal cells influenced particularly a loss of E-cadherin expression (r = −0.35, p=0.12; Pearson), thereby pointing to a possible collaborative implication of IL-17 and TGF-β to EMT induction." (PMID 31885577, 2019).
tumor (continued). "Moreover, IL-17A has been detected in several human tumors, where it has been associated with pro-tumorigenic effects, and particularly with resistance to cancer therapies, by acting on cancer cells and also on the tumor microenvironment." (PMID 29371916, 2017). "We identify several Th17–Treg transdifferentiation-associated transmembrane molecules on IL-17A+Foxp3+ cells that may be feasible targets to manipulate Treg cell-associated tumour immune surveillance, and complement programmed cell death protein 1 (PD1)-mediated control of T-cell activation." (PMID 28290453, 2017). "Therefore, blocking IL-17A at tumor sites decreased MDSCs and Treg cells and caused the Th1 shift." (PMID 23372655, 2013). "Tumor cells subvert immunity by suppressing IFN-γ in CD4+ T cells via Wnt signaling while promoting IL-17a production, thereby impairing antitumor surveillance." (PMID 41515289, 2026). "Tc17 cells, which produce IL-17A, increase tumor cell proliferation and survival, contributing to poor prognosis." (PMID 40536951, 2026). "In HCC, tumor-derived type 3 innate lymphoid cells (ILC3s) promote hepatic stellate cell (HSC) activation via an IL-17A-dependent pathway, driving liver fibrosis, which is associated with poor patient prognosis 62,63." (PMID 41355959, 2026). "Conditional ablation of SFB-induced IL-17A+CD4+ T cells, precursors of tumour-associated TH1-like cells, abolishes anti-PD-1-mediated tumour control and markedly impairs tumour-specific CD8+ T cell recruitment and effector function within the TME." (PMID 41535459, 2026). "In pancreatic ductal adenocarcinoma, IL-17A promotes tumor progression by inducing the differentiation of cancer-associated fibroblasts via IL-17RA and TNF signaling, creating a tumor-promoting stromal environment." (PMID 40536951, 2026). "In summary, IL-6, TNF-α, IL-17A, and CXCL8 (IL-8) emerge as the cytokines most strongly linked to promoting anoikis resistance in tumor cells, activating survival pathways like NF-κB, STAT3, and AKT/ERK." (PMID 41596231, 2026). "IL-23 stabilizes the Th17 phenotype and promotes expression of pro-tumor mediators such as IL-17A, IL-22, and GM-CSF, while inhibiting anti-tumor features such as IFN-γ production." (PMID 41181112, 2025). "This cell subgroup inhibits anti-cancer responses by producing immunosuppressive adenosine, and promotes angiogenesis as well as tumor development by releasing pro-inflammatory IL17A." (PMID 41019045, 2025). "In patients with asthma, overexpression of IL-26 is associated with elevated expression of IL-17A, RAR-related orphan receptor C (RORC), IL-1β, IL-6, and tumor TNF, driven by activation of the IL-20R1/IL-10R2 receptor complex." (PMID 41516201, 2025). "Further, ablation of γδ T cells or IL-17A blockade or MDSC depletion combined with intact γδ T cell populations yielded improved tumor regression and survival after radiotherapy in murine models." (PMID 41392975, 2025). "Subsequent analysis revealed a robust positive correlation among the expressions of IL-22, IL-26, and IL-17A, with their corresponding receptors were notably elevated in the tumor samples." (PMID 40452847, 2025). "In early-stage GC, IL-17A can activate the NF-κB pathway and induce stromal remodeling, leading to enhanced tumor proliferation." (PMID 40510364, 2025). "Studies have shown that IL-17A and its receptor, IL-17RA, are overexpressed in CRC tissues and are associated with tumor progression and poor prognosis." (PMID 40725273, 2025). "In endometrial cancer, uterine-infiltrating CD68+CD163+ macrophages induce ERα expression through IL-17A-mediated epigenetic mechanisms, sensitizing cancer cells to E2 and accelerating tumor progression." (PMID 40303343, 2025). "The data suggest that all three interleukins—IL-8, IL-17A, and IL-33—tend to be more elevated in well-differentiated tumors (G1) and decline with increasing tumor grade." (PMID 40725273, 2025).
tumor (continued). "Although most cytokines changed in the tumor induced by BNT162b2 play a role in tumor-killing, there was a significant decrease in intratumoral IL-4, and significant increases in intratumoral IL-13 and peripheral IL-17A." (PMID 39743545, 2025). "Naive gut-specific T cells were capable of trafficking to the lung and differentiating into IL-17A-producing effectors only when the appropriate microbial signals and tumor antigens were present." (PMID 41441899, 2025). "Our data indicate that Tc17 cells highly express a range of cytokines, notably IL-16, IL-17A, IL-17F, IL-22, and IL-26, and it is these five cytokines for which receptors are also highly expressed in tumor cells." (PMID 40452847, 2025). "APS-1 patients carry AIRE mutations that lead to autoantibodies against IL-17A/F, IL-22 and type I interferons (IFN-α/ω) and impair Th17 antifungal immunity and tumor surveillance." (PMID 41009535, 2025). "Our multiple regression analysis further revealed a significant, nonlinear correlation between IL-8 and IL-17A in relation to tumor invasion, with the model accounting for 43.56% of the variance in IL-17A expression." (PMID 40725273, 2025). "Concurrently, IL-17A enhances CXCL5 production in tumor cells and promotes MDSC migration at the tumor site through a CXCR2-dependent mechanism, facilitating tumor progression and immune evasion." (PMID 40558272, 2025). "In aged OVX 67NR tumor-bearing mice, tacalcitol decreased Il17a expression, while calcitriol reduced Foxp3 expression." (PMID 40894304, 2025). "In triple-negative breast cancer models, OC’s dual inhibition of IL-6/STAT3 and COX-2/mPGES-1 pathways reduced Th17/Treg cross-talk by 40%, diminishing IL-17A-driven PD-L1 expression on tumor cells while augmenting CD8+ T cell cytotoxicity." (PMID 40564985, 2025). "In mice, γδ T cells mediate many pro-tumor functions through expression of IL-17A, a pleiotropic cytokine that modulates the behavior of both cancer and immune cells." (PMID 40422223, 2025). "The increased expression of IL-17A we observed in PCa patients agrees with several previous studies, although most of them analyzed IL-17 expression in the tumor tissue and microenvironment." (PMID 40427694, 2025). "IL-17A signaling within tumor cells triggers the secretion of CXCL5, leading to the subsequent recruitment of MDSCs." (PMID 40497988, 2025). "Infiltration of IL-17A-secreting γδ T cells correlates with advanced tumor stages, larger tumor size, lymphatic and vascular invasion, and lymph node metastasis." (PMID 40136652, 2025). "IL-17A is a pro-inflammatory cytokine that drives intestinal tumorigenesis and it is required for tumor formation in ApcMin/+ mice." (PMID 40022152, 2025). "While this p-value does not meet the conventional α = 0.05 threshold for statistical significance, it suggests a trend of decreasing IL-17A levels with increasing tumor grade." (PMID 40725273, 2025). "Mechanistically, our data revealed that KRAS knockdown affects tumor metastasis by inactivating IL-17 signal pathway via IL-17A-dependent manner." (PMID 40486048, 2025). "IL17A recruits and activates neutrophils in the tumor immune microenvironment by inducing the production of IL-6 in their research." (PMID 41254689, 2025). "While IL-17A plays dual roles in cancer biology, emerging evidence suggests that its anti-tumor or pro-tumor effects depend on its cellular source." (PMID 41155334, 2025). "Like ILCs, type 2 primed ILTCs encourage cancer growth and spread, while type 17 polarized ILTC release IL-17A, enhance angiogenesis, and promoting tumor growth." (PMID 40352926, 2025). "A combined model incorporating IL-8, IL-17A, IL-33, and tumor grade accounted for over 70% of IL-17A variability, underscoring their interactive role in CRC biology." (PMID 40725273, 2025).